PRB4 (proline rich protein BstNI subfamily 4)
Synonyms: Po
Gene: Protein-coding gene on chromosome 12 (11,307,077 to 11,310,436, reverse strand). Ensembl gene ENSG00000230657.
Subcellular location: Secreted
Genetic constraint (gnomAD): Loss-of-function variants: 14 observed, 9.31 expected, observed/expected ratio (o/e) 1.5, 90% interval 0.97 to 1.93. That is too few expected variants to judge how well the gene tolerates losing a copy. Missense variants: 380 observed, 284.61 expected, observed/expected ratio (o/e) 1.34, 90% interval 1.23 to 1.45. Synonymous variants: 102 observed, 104.01 expected, observed/expected ratio (o/e) 0.98, 90% interval 0.83 to 1.16.
Homologues: Paralogues in human: PRB3 (82% identical), PRB2 (77% identical), PRB1 (61% identical), PRH1 (42% identical), PRH2 (39% identical), PRR4 (20% identical).
Diseases named in the same sentence as PRB4 in open-access papers:
PRB4 is named in the same sentence as 8 diseases in open-access papers, as found by Europe PMC text mining. Sharing a sentence is not in itself a finding about the gene and the disease. The quoted sentences say what the papers report.
dental caries (1 paper, 2023). The decay of a tooth, in which it becomes softened, discolored, and/or porous. "Genetically, genes such as PRB4 and DEFB1 have been reported to be associated with the progression of dental caries due to variation." (PMID 37928602, 2023). "This study focused on several reported genes associated with the progression of dental caries that have variants between the Han1 and BKY populations, including PRB4, which encodes a proline-rich alkaline salivary protein." (PMID 37928602, 2023).
hypopharyngeal carcinoma (1 paper, 2017). Carcinoma, predominantly squamous cell, arising from the epithelial cells of the hypopharynx. "We knocked down PRB4 expression hypopharyngeal carcinoma cells, and found that downregulation of PRB4 could inhibit cell growth, colony formation and cell invasion, and we speculate that the mutations in this gene enhanced it oncogenic effects." (PMID 29156722, 2017). "PRB4 and NSD1 expression were significantly upregulated in hypopharyngeal carcinoma, which was confirmed in an independent cohort using IHC." (PMID 29156722, 2017). "We also indentify a novel epigenetically regulatory between PRB4 and NSD1 that contribute to hypopharyngeal carcinoma tumorigenesis." (PMID 29156722, 2017). "We found that PRB4 and NSD1 were dramatically increased in hypopharyngeal carcinoma tissues compared with adjacent tissues." (PMID 29156722, 2017). "Therefore, PRB4 and NSD1 mutations might contribute to hypopharyngeal carcinoma tumorigenesis." (PMID 29156722, 2017). "We focused on the role of PRB4 and NSD1 in hypopharyngeal carcinoma." (PMID 29156722, 2017). "Thus, the results suggest that PRB4 and NSD1 might contribute to the development of hypopharyngeal cancer." (PMID 29156722, 2017). "However, the functions of PRB4 and NSD1 (nuclear receptor binding SET domain protein 1) are not clear in hypopharyngeal carcinoma." (PMID 29156722, 2017).
hypopharyngeal tumor (1 paper, 2017). "In addition, we further investigate the function of PRB4 in hypopharyngeal tumor and the underlying mechanisms." (PMID 29156722, 2017). "In this study, we performed whole-exome sequencing (WES) of 23 hypopharyngeal tumor and paired adjacent normal tissue and confirmed the expression of NSD1 and PRB4 in an independent cohort containing 88 hypopharyngeal tumor and 36 adjacent normal tissues." (PMID 29156722, 2017).
lymphoma (1 paper, 2025). A malignant (clonal) proliferation of B- lymphocytes or T- lymphocytes which involves the lymph nodes, bone marrow and/or extranodal sites. "The significance of the PRB4 mutation is uncertain; but given it was present at low VAF and not previously reported in lymphoma, it is unlikely of significance in AITL." (PMID 39877932, 2025).
tumor (1 paper, 2017). "Univariate analysis data indicated that the PRB4 level (P=0.013) and NSD1 level (P=0.010), as well as the tumor size (P=0.027), metastasis (P=0.006), and clinical stage (P=0.008) was significantly associated with the survival." (PMID 29156722, 2017).
PRB4 also shares sentences with these, for which no sentence is quoted: infection (5 papers); gastric cancer (1); Insulin resistance (1).